HOXA10 (homeobox A10)
Diseases named in the same sentence as HOXA10 in open-access papers (continued):
Sharing a sentence is not in itself a finding about the gene and the disease.
Infertility (continued). "Additionally, studies using human endometrial tissue identified miR-135b to be elevated in infertile women, and this miRNA is shown to downregulate homeobox A10 (HOXA10) expression." (PMID 35682889, 2022). "Mice with multiple combinations of mutations of either the Hox10 or Hox11 paralog groups have interesting kidney and limb abnormalities, but no described infertility phenotypes extending beyond those associated with the Hoxa10 and Hoxa11 genes." (PMID 30872674, 2019). "Since pregnancy was achieved for some of the infertile women, this does posit that an uncharacterized alternative mechanism could promote implantation and pregnancy under certain HOXA10 and MUC1 expression conditions." (PMID 28830391, 2017). "Recently, women with varying reasons of infertility were shown to have reduced HOXA-10 levels." (PMID 28830391, 2017). "The homozygous mutation of HOXA10 does not affect ovarian reserve but often results in infertility." (PMID 39795629, 2025). "Therefore, HOXA10 gene expression in mid-secretory endometrium has been reported as a receptivity marker that could assist the diagnosis of implantation impairment in infertile women." (PMID 32685419, 2020). "Of interest, while the Hoxa10 and Hoxa11 genes have defined functions in female fertility, single homozygous mutation of the paralogous Hoxc10, Hoxd10, Hoxc11 and Hoxd11 genes gave no reported infertility." (PMID 30872674, 2019). "Given the potential indirect influence of male-factor infertility on endometrial receptivity, we additionally examined the expression of key endometrial functional markers—FOXO1, HAND2, HOXA10, and KI67—in both groups." (PMID 41199770, 2025). "The expression levels of HOXA10 and EMX2 have been shown to decrease and increase consecutively in infertile women with MDAs." (PMID 37629050, 2023). "As shown by IHC, HOXA10 and FHL1 expression was significantly lower (p < 0.05) in the endometrial epithelial and stromal cells of infertile women with a GTD history than in those of the controls." (PMID 35120557, 2022). "A study analyzing endometrial HOXA10 and HOXA11 levels during the WOI in infertile women with intramural UFs found significantly decreased levels of HOXA10 and HOXA11 and a slight decrease in E-cadherin compared to healthy fertile women." (PMID 34113609, 2021). "HOXA10, EMX2, TENM1 mRNA and protein expression levels differ significantly in mid-secretory endometrium in infertile women with a Mullerian duct anomaly compared with controls." (PMID 31844537, 2019). "Female mice lacking HOXA10 have been reported to experience spontaneous abortion and infertility owing to implantation and decidualization failure." (PMID 38576003, 2024). "Pearson’s correlation coefficient on the expression of miRNA-135b and mRNA HOXA-10 mRNA in endometrium samples of the infertile group revealed a significant negative correlation between the two variables (p=0.021; r=−0.607)." (PMID 32685419, 2020). "The reduction or absence of HOXA10 in the uterine endometrium leads to infertility due to the inability of the embryo to implant [11•]." (PMID 27217980, 2016). "In an animal model, the reduction or absence of HOXA10 in the uterine endometrium leads to subfertility or infertility due to the inability of the embryo to implant." (PMID 28620517, 2015). "The lack of significant change in HOXA10 expression in the endometrial tissue of women with EP in this study supports the idea that mechanical effects and local factors, rather than changes in genetic expression, may primarily mediate the relationship between polyps and infertility." (PMID 39915377, 2025). "However, emerging evidence suggests that miR-1910-3p may influence infertility, as studies in patients with polycystic ovary syndrome have demonstrated its role in regulating endometrial receptivity through modulation of Integrin beta-3 subunit (ITGB3) and Homeobox A10 (HOXA10) expression." (PMID 40565325, 2025).
Infertility (continued). "The expression of HOXA10 and HOXA11 during theproliferative phase is not significantly different between infertile women withendometritis and infertile women without endometritis." (PMID 38801313, 2024). "The expression of HOXA10 and HOXA11 duringthe proliferative phase is not significantly different between infertilewomen with endometritis and infertile women without endometritis.Translational studies with a larger number of patients should beperformed." (PMID 38801313, 2024).
leukemia (45 papers, 2007 to 2025). A malignant (clonal) hematologic disorder, involving hematopoietic stem cells and characterized by the presence of primitive or atypical myeloid or lymphoid cells in the bone marrow and the blood. "Somewhat surprisingly, the list of target promoters failed to include most MLL-AF9 ChIP targets with the leukemia self-renewal associated Hox gene signature, namely Hoxa9, Hoxa10 and Meis1, escaping Kat2a-dependent promoter acetylation control." (PMID 31985402, 2020). "HoxA9 and HoxA10 are increased in cells expressing Mll-Ell, a leukemia-associated MLL1 fusion protein." (PMID 25531430, 2014). "Leukemia-associated, constitutively active mutants of Shp2 block cytokine-induced tyrosine phosphorylation of HoxA9 and HoxA10." (PMID 25531430, 2014). "Moreover, changes to MEIS/HOXB13 transcriptional regulation or interaction by HOXB13 mutations could enable MEIS proteins to pair with HOXA9 or HOXA10 to drive oncogenesis and progression, such as in leukemia or ovarian cancer." (PMID 32553107, 2020). "Experimental mouse models reveal that high-level expression of BCR::ABL alone is insufficient to induce leukemia, whereas co-expression with Setbp1, Hoxa10 or Hoxa9 produces aggressive leukemia within 3 weeks." (PMID 41179655, 2025). "RNA-seq analysis of A485-treated K/C-III leukemia cells further revealed significant downregulation of key hematopoietic factors, including Hoxa9, Hoxa10, Meis1, Cd34, c-Kit, and Csf1r." (PMID 40830799, 2025). "They explored the related regulators of HOXA10, such as the V-ATPase pump and the Trithorax protein mixed lineage leukemia." (PMID 37351805, 2023). "HOXA9 induces breast cancer and leukemia, and HOXA10 is an oncogene of prostate and testicular cancers." (PMID 37834206, 2023). "Both HOXA9 and HOXA10 were reported to be highly expressed and significantly correlated with leukemia progression and/or maintenance." (PMID 33037410, 2020). "Compared to levels in Hoxa9/Meis1 leukemias, endogenous Hoxa9 and Hoxa10 were considerably elevated in SQSTM1-NUP214 leukemias, whereas the levels of Hoxa3, Hoxa5, Hoxa7, Hoxa11 and Meis1 were comparable in Hoxa9/Meis1 and SQSTM1-NUP214 leukemias." (PMID 32343715, 2020). "Even so, it is known that the HOXA10 gene has oncogenic potential in developing leukemia; specific roles of HOXA5, HOXA7, and HOXA10 in myeloid leukemias are poorly described." (PMID 31681584, 2019). "Consistent with their co-transduction by BCR/ABL and Hoxa10 viruses, these leukemia cells expressed high levels of BCR/ABL and Hoxa10." (PMID 29228732, 2017). "Our results identify a mechanism for increased and sustained CDX4 transcription in leukemias co-overexpressing HoxA9 and HoxA10 in combination with constitutive activation of Shp2." (PMID 25531430, 2014). "The activation of OXPHOS in HOXA10-high patients may promoted leukemia cell maintenance and chemo-resistance, leading to inferior survival." (PMID 32571260, 2020). "Importantly, the NUP98 translocations that occur in AML all share the N-terminus of the protein and are thought to initially lead to epigenetic dysregulation of different leukemia-associated genes including HOXA7, HOXA9, and HOXA10 in myeloid precursor cells." (PMID 31467532, 2019). "Interestingly, we found that all mice receiving GMPs co-transduced by BCR/ABL and Hoxa10 viruses also developed myeloid leukemias, although with longer latencies than leukemias induced by Hoxa9+BCR/ABL." (PMID 29228732, 2017). "Notably, a recent report also demonstrated that Crm1 binds to the HoxA9 and HoxA10 gene regions, both in human leukemia cell line and immortalized mouse embryonic fibroblast cell line." (PMID 26740045, 2016). "Furthermore, high level expression of CD44 by leukemia cells was sufficient to generate leukemia by leukemia-initiating cells even after withdrawal of overexpression of the HoxA10 gene that initiated the leukemia." (PMID 22346731, 2012).
leukemia (continued). "This interpretation is supported by the general enrichment of genes overexpressed in dendritic cells and in leukemia, as well as by enrichment of the patterning gene HOXA10 and by the specific downregulation of PLZF in hemangiosarcomas; both of which are involved in hematopoietic differentiation." (PMID 21062482, 2010). "Two of the selected genes could not be detected in the majority of the samples in either normal or leukemia bone marrow (HOXA10 and DDX4) and were therefore excluded from further analysis." (PMID 17712416, 2007). "Finally, we performed gene expression studies in MLL-AF9 and MLL-AF6 transformed bone marrow cells and found that genes highly relevant to MLL leukemia (Hoxa5, Hoxa9, Hoxa10, Meis1, and Mef2C) were expressed at much lower levels in the ΔSET Ash1l versus WT Ash1l cells." (PMID 33990599, 2021). "Based on these studies, it can be speculated that, during EG in leukemia, overexpression of HOXA10 leads to sustained activation of TRIAD1, which favors a suppressed EG state, thus identifying one factor that may cause neutropenia in leukemia patients and make them more susceptible to infections." (PMID 29593731, 2018). "In leukemia, HBO1 upregulates HOXA9 and HOXA10 expression through H3K14 acetylation, maintaining leukemia stem cell characteristics." (PMID 39543485, 2024). "STM2457, the first METTL3 inhibitor, was validated to reduce the m6A deposit on several oncogenes (such as HOXA10 and MYC), induce cell differentiation, and effectively inhibit the growth of leukemia cells." (PMID 37028765, 2023). "HOXA9, HOXA10, and HOXA7 are induced by MLL-AF4 and HOXA9 is required for MLL-rearranged leukemia survival." (PMID 34321607, 2022). "Other key leukemia-specific hits include MYB, MED13L, HOXA10, and the binding partner of RUNX1, CBFB." (PMID 34088716, 2021). "This set of target genes was also confirmed in leukemias induced in mice transformed by MLL-AF9 (HoxA9, HoxA10, Evi1 (MECOM), HoxA2, HoxA7 HoxA3, and HoxA13) and also induced iMLL-AF9 in mice HoxA9, HoxA10, Meis1, Eya1, Mef2c, Myb, and Six1." (PMID 34639154, 2021). "Conversely, the PLXND1, PLCB4, HOXA9, HOXA10, TLX3, and NKX2‐1 genes had higher expression in the CIMP+ subgroup, compared to the normal T cells and CIMP− leukemias." (PMID 30575306, 2019). "Together, this demonstrates unique dependency on a subset of the Hoxa cluster (Hoxa7, Hoxa9, Hoxa10, and Hoxa11) genes for maintenance of MA9 leukemia." (PMID 31861091, 2019). "Recent genome-wide ChIP-seq analyses identified various sets of direct target genes of MLL-FP, which consistently included the master regulatory factors (HOXA7, HOXA9, HOXA10, and MEIS1) required for the development of MLLr-leukemias." (PMID 29692408, 2018). "Different from GMP-derived leukemias induced by Setbp1 and BCR/ABL, Hoxa9+BCR/ABL and Hoxa10+BCR/ABL leukemias are mostly monoclonal in origin, suggesting that additional mutation(s) is likely required for the transformation in both cases." (PMID 29228732, 2017). "Our results also suggest that Hoxa9 is more potent than Hoxa10 in inducing CML myeloid blast crisis, as the Hoxa9+BCR/ABL mice developed leukemia with a significantly shorter latency than Hoxa10+BCR/ABL mice." (PMID 29228732, 2017). "In summary, our results identify overexpression of HOXA9, HOXA10, and MYB as critical drivers of CML progression, and suggest MYB as a key therapeutic target for inhibiting the self-renewal of leukemia-initiating cells in CML myeloid blast crisis patients." (PMID 29228732, 2017). "Resembling mice with Hoxa9+BCR/ABL and Hoxa10+BCR/ABL leukemias, the bone marrow, spleen and liver of the moribund mice were infiltrated by immature leukemia blasts, representing 31 ± 5.7% (Mean ± SD) of all nucleated cells in the bone marrow." (PMID 29228732, 2017). "These leukemia cells also displayed a similar lineage marker expression profile to that of Hoxa9+BCR/ABL and Hoxa10+BCR/ABL leukemia cells and were transplantable." (PMID 29228732, 2017).
leukemia (continued). "In acute myeloid leukemia, miR-204 targets HOXA10 and MEIS1, two members of the homeobox family of transcription factors involved in leukemia development." (PMID 20302635, 2010). "We reasoned that the lower expression levels of HOXA9 and HOXA10 probably were a reflection of slower progressing of leukemia rather than a HoxB13 shRNA non-specific knockdown effect on the HoxA family members." (PMID 33037410, 2020). "Again, none of the recipient mice for GMPs singly infected with Hoxa10 or BCR/ABL virus developed leukemia." (PMID 29228732, 2017). "Leukemias with chromosomal translocations of the mixed lineage leukemia 1 (MLL1) gene are characterized by increased and sustained transcription of a group of HOX genes (including HOXA10), as fusion proteins generated by MLL1 gene translocations lack ubiquitination/degradation domains." (PMID 29593731, 2018). "In addition, these leukemia cells did not express detectable levels of Hoxa9 or Hoxa10 protein, suggesting that their transformation is independent of Hoxa9 or Hoxa10 activation." (PMID 29228732, 2017). "While the expression of the stem‐related gene HOXA10 is not significantly different between NPM1, KMT2Ar, and NUP‐r harboring leukemias, we found that HOPX expression is significantly different between KMT2Ar and NUP‐r in comparison to NPM1." (PMID 41178390, 2025). "The 75KDa form also is predominantly expressed in Hoxa9- and Hoxa10-immortalized myeloid progenitors and Hoxa9/Hoxa10+BCR/ABL leukemia cells (data not shown)." (PMID 29228732, 2017). "MSP, RT–PCR and Western blot were performed to respectively analyse the methylation status of HOXA10 promoter CpG island, mRNA expression of MLL1 and HOXA10, protein expression and H3K4 methylation status in the leukaemia cell line (HL-60) with and without MLL1 knockdown." (PMID 25307539, 2014).
breast carcinoma (24 papers, 2011 to 2023). "For example, HOXA10 overexpression promotes endometrial cancer and HNSCC activities, whereas HOXA10 inhibition is associated with breast cancer tumorigenesis." (PMID 30581773, 2018). "HOXA10, which encodes a transcription factor required for embryonic development and is a metastasis suppressor in breast cancer, was shown to be a direct target of miR-135a in breast cancer cells." (PMID 22439757, 2012). "In this study, we show that a combination of HOXA9 and HOXA10 promoter methylation markers is significantly associated with the prognosis of breast cancer patients in independent datasets and compose a transcriptional regulation module through long-range chromatin interactions." (PMID 28748001, 2017). "Of specific interest, HOXA10 has been shown to be under the control of miR-135a in endometrial and epithelial cancer tissues which led us to ask if miR-135a might also be associated with breast cancer." (PMID 22439757, 2012). "It has been reported that miR-135a enhances invasion and migration of breast cancer cells by regulating HOXA10." (PMID 33686957, 2021). "Among the 4 genes, RASGRF1 and CPXM1 represented common breast cancer marker, while HOXA10 and DACH1 represented luminal-dominant marker and triple negative dominant marker, respectively." (PMID 32550045, 2020). "In the setting of cancers, HOXA10 deregulation is known to play significant roles in mammary carcinoma, endometrial carcinoma, head and neck squamous cell carcinoma (HNSCC)." (PMID 30581773, 2018). "The combination of long-range interacting HOXA9 and HOXA10 promoter CpGs predicted the survival of breast cancer patients, providing a comprehensive and novel approach for discovering new methylation markers." (PMID 28748001, 2017). "To assess the value of the combination of the HOXA9 and HOXA10 promoter CpG methylation markers as a prognostic marker for breast cancer, we performed a multivariate Cox proportional hazards analysis with other subtype markers." (PMID 28748001, 2017). "Using the survival data, we examined the association between the survival rate of breast cancer patients after surgery and the DNA methylation of each of the six CpGs on the HOXA9 and HOXA10 promoters." (PMID 28748001, 2017). "We suggest that the promoter-promoter interaction between HOXA9 and HOXA10 is important in breast cancer progression through the enhancer-like action of HOXA10 promoter CpGs." (PMID 28748001, 2017). "We used bioinformatic tools and the literature to identify HOXA10 as a miR-135a target gene candidate and verified it is directly regulated by miR-135a in breast cancer cells." (PMID 22439757, 2012). "In breast cancer cell lines, expressing miR-135a by transfection of pS-135a reduced the endogenous HOXA10 protein expression in MCF-7 cells and BT549 cells." (PMID 22439757, 2012). "To further investigate the effect of HOXA10 on breast cancer cell invasiveness, we overexpressed HOXA10 in already highly invasive breast cancer cell lines." (PMID 22439757, 2012). "Because HOXA10 is a confirmed miR-135a target in more than one tissue, we examined miR-135a levels in relation to breast cancer phenotypes to determine if miR-135a plays role in this cancer type." (PMID 22439757, 2012). "To verify HOXA10 is a real target of miR-135a in breast cancer, we first tested if HOXA10 is co-expressed with this miRNA." (PMID 22439757, 2012).